USP28 (ubiquitin specific peptidase 28)
Diseases named in the same sentence as USP28 in open-access papers (continued):
Sharing a sentence is not in itself a finding about the gene and the disease.
cancer (continued). "Similarly, USP28 is a DUB that stabilizes the c-Myc transcription factor, a potent oncogene in a wide variety of human cancers, and inhibiting USP28 is expected to reduce the levels of c-Myc, and downregulate its activities." (PMID 35737447, 2022). "The emerging roles of USP28 in cancer pathways have been discovered by some recent studies." (PMID 34502538, 2021). "The increased basal levels of DNA damage presented in cancer cells could induce phosphorylation of USP28, thereby allowing the stabilization of USP28 substrates independently of E3-ligases in cancer cells." (PMID 34685632, 2021). "The USP28 deubiquitinase has been recognized as a promising therapeutic target for cancer." (PMID 33572615, 2021). "Therefore, it is not surprising that different pharmaceutical companies and research groups have tried to develop efficient USP28 inhibitors as drugs to target cancer cells." (PMID 34685632, 2021). "USP28 is also reported to control c-Myc driving cancer cells and the stability of c-Myc." (PMID 33572615, 2021). "To investigate whether loss of USP28 may affect glycogen metabolism in carcinoma, we compared glycogen accumulation in DEN-induced HCC of WT and Usp28-KO mice using Periodic acid-Schiff (PAS) staining." (PMID 32927708, 2020). "Furthermore, H2A deubiquitinases, such as BAP1, USP14 and USP28, have been shown to suppress proliferation and increase radiosensitization in human cancers." (PMID 31761786, 2019). "The clinical implications of dysregulated USP28 have been documented for various cancers as well." (PMID 29415985, 2018). "The cancer-promoting role of USP28 was confirmed by in vitro assays where overexpressing USP28 could enhance NSCLC cell proliferation while downregulating it induced apoptosis." (PMID 29415985, 2018). "Depletion of USP28 in some cancer cell lines phenocopies the effect of MYC depletion." (PMID 29415985, 2018). "Below, we will review the advances in USP28-targeted cancer therapy." (PMID 29415985, 2018). "This fact adds another layer of complexity regarding the roles of USP28 in cancer-related pathways." (PMID 29415985, 2018). "Answers to this question can promote our understanding of the pathophysiological implications of USP28-mediated regulation on genotoxicity and cell cycle progression, which may shed light on improving strategies for cancer therapy." (PMID 29415985, 2018). "The emerging roles of USP28 in cancer pathways have been revealed by some recent studies." (PMID 29415985, 2018). "Notably, USP28 mutants found in cancer may retain the ability to stabilize MYC, thus maintaining oncogenic signaling." (PMID 41365927, 2025). "In addition to its role in the DDR, USP28 was also demonstrated to stabilize the c-MYC oncogene by antagonizing its ubiquitin-mediated degradation by the ubiquitin ligase FBW7 that is frequently lost in cancers." (PMID 39398482, 2024). "Thus, we envision that inhibiting the regulation of MAST1 protein abundance by USP28 in cisplatin-resistant cancer cells may be effective alternative therapeutic strategy to overcome cisplatin resistance in cancer patients." (PMID 38498222, 2024).
cancer (continued). "Precisely what selective pressures drive the loss of 53BP1 and USP28 in cancer remains to be determined, but current data supports the proposition that MSP gene status could be used as a potential biomarker for poor responses to antimitotic drugs in cancer." (PMID 39398482, 2024). "Therefore, our results indicate that USP28 could influence cancer development and prognosis by changing the tumor microenvironment." (PMID 37450415, 2023). "Therefore, targeting deubiquitinase USP28 for cancer therapy is very important." (PMID 37450415, 2023). "USP28, as a critical member of a family of deubiquitinating enzymes, is involved in many physiological and pathological progress of cancers, including physiological homeostasis of the ubiquitination process, DNA-damage response, apoptosis, cancer migration, differentiation." (PMID 37450415, 2023). "Therefore, we explored the consequences of USP28 CNV status in various cancer." (PMID 37450415, 2023). "As cancer panel sequencing is implemented in the clinics and pathway‐specific inhibitors are available, we were wondering whether disruption of the oncogenic pathways would directly affect USP28 and hence the abundance of its downstream effectors." (PMID 35364627, 2022). "In addition to affecting the turnover of critical oncoproteins like MYC, USP28 may regulate other essential pathways in cancer progression." (PMID 29415985, 2018). "Regardless, USP28 may be a potentially beneficial therapeutic target for cancer treatment." (PMID 29415985, 2018). "USP28 and TP53BP1 are also significantly enriched in genome-wide screenings for resistance to anti-cancer drugs (in 6 or 9 out of the 10 anticancer drug screens, for TP53BP1 or USP28, respectively)." (PMID 40082762, 2025). "By binding to ubiquitin-specific peptidase 28 (USP28), ExomiR-500a-5p was transported from CAFs to the cancer cells, where it promoted proliferation and metastasis." (PMID 38455764, 2024). "The expression pattern of USP28 and MAST1 showed a positive correlation across a panel of tested cancer cell lines and human clinical tissues." (PMID 38498222, 2024). "FBW7 is highly mutated across cancers and leads to multidrug resistance (MDR), suggesting that this could be phenocopied by USP28 loss or amplification in some cancer types, although this this is not borne out in the CRISPR screening data that identified FBW7 in this role." (PMID 39398482, 2024). "Depletion of USP28 destabilized MAST1 protein levels and also sensitized cisplatin-resistant cancer cells for cisplatin-mediated cytotoxicity." (PMID 38498222, 2024). "We demonstrated that USP28 interacts and regulate MAST1 protein stabilization in cisplatin-resistant cancer cells." (PMID 38498222, 2024). "We further analyzed the expression of USP28 and MAST1 in a wide range of cancer cell lines using the Cancer Cell Line Encyclopedia (CCLE) database." (PMID 38498222, 2024). "Thus, USP28 may be a potential therapeutic target along with MAST1 to synergistically boost the effect of cisplatin-based treatment to overcome cisplatin resistance in cancer patients." (PMID 38498222, 2024). "We used the TCGA database to evaluate the normal-tumor matched mRNA expression level of USP28 and MAST1 in different cancer types." (PMID 38498222, 2024). "Depletion of USP28 resulted in the destabilisation of mature SREBP2, reduced expression of MVP enzymes and rendered cancer cells highly sensitive to MVP inhibition by statins, which was rescued by precursors of protein prenylation." (PMID 37202505, 2023). "Exosomal miR-500a-5p molecule affects the expression level of ubiquitin-specific peptidase 28 (USP28) through targeting transport, and ultimately promote cancer proliferation and metastasis." (PMID 36759842, 2023).
cancer (continued). "These DUBs (USP22, USP28, USP29, USP36, USP37 and OTUD6A) are observed in stabilizing MYC in cancer cells." (PMID 36765885, 2023). "In most TCGA cancers, except for SARC and TGCT, there was a strong positive correlation between USP28 and CD276 and Neuropilin-1 (NRP1)." (PMID 37450415, 2023). "This study illustrated that USP28 expression was significantly connected with TMB and MSI in most cancers." (PMID 37450415, 2023). "And especially, USP28 was significantly correlated with NRP1, CD276, ADORA2A, and TNFSF15 in most cancers." (PMID 37450415, 2023). "The reported deubiquitinases of MYC include USP22, USP28, USP29, USP36 and USP37, and they enhance cancer stemness via BMI1, LSD1 Snail and CEP63 stabilization, respectively." (PMID 36765885, 2023). "Ultimately, USP28 induces the tumorigenic function of LIN28A and enhances the viability and migration of cancer cells, increasing LIN28A-mediated tumor progression." (PMID 35806250, 2022). "USP28 can counteract the activity of FBW7 and promote the stability of FBW7-substrates in cancer cells." (PMID 33664871, 2021). "Alternatively, in already transformed cancer cells and particularly in SCC cancer cells, USP28 acts as an oncoprotein facilitating cancer homeostasis and proliferation via stabilization of oncogenic substrates, such as c-MYC, c-JUN, NOTCH1, ∆Np63, and CCNE." (PMID 34685632, 2021). "Recently, however, as the structural similarities and differences between USP25 and its homolog USP28 have become clear, mechanisms of action of USP25 in cancer and other diseases have been gradually revealed." (PMID 34249948, 2021). "USP28 is a deubiquitinase that has been shown to stabalise LSD1 and MYC, an important regulator of gene expression, to promote a cancer stem-cell like state and proliferation." (PMID 30323900, 2018). "Disrupting USP28 leads to LSD1 destabilization, which suppresses cancer stem cell-like characteristics in vitro and inhibits tumorigenicity in vivo." (PMID 29415985, 2018). "Moreover, USP28 depletion reduces mevalonate activity and sensitizes NSCLC cancer cells to statins by modulating SREBP2 through deubiquitination." (PMID 40855785, 2026). "USP28 stabilizes key oncoproteins, such as c‐MYC, c‐JUN, and TCF7L2, by preventing their proteasomal degradation, thereby promoting tumorigenesis in various cancers, including breast cancer and hepatocellular carcinomas." (PMID 40855785, 2026). "A defining feature of USP28 is its antagonistic relationship with the E3 ubiquitin ligase FBXW7, stabilizing oncoproteins such as c-Myc and NOTCH1, a mechanism particularly relevant in cancers characterized by FBXW7 depletion." (PMID 40858801, 2026). "CT1113 can reduce c‐MYC levels and inhibit USP28 and USP25 in various cancer cell lines, resulting in decreased expression of MYC–MAX target genes and increased ubiquitination of substrates like c‐MYC and Tankyrase, thus exhibiting a broad‐spectrum anticancer activity." (PMID 39678489, 2024). "The decisive role of USP28 and USP25 in maintaining elevated cellular levels of different ‘hard to drug’ cancer-promoting proteins has rendered both DUBs highly attractive targets for the development of small-molecule inhibitors against different cancers." (PMID 38816515, 2024). "Next, with the HEPIA2 database support, we exhibited a significant correlation between USP28 expression and the pathological stages of some cancers, including KIRC, PAAD, and LIHC but not others." (PMID 37450415, 2023). "To elucidate the cancer type spectrum of the USP28 phenocopies, we considered the USP28 amplifications as a negative control (in this gene, deletions are expected to phenocopy)." (PMID 37095494, 2023). "Finally, we identified the involvement of USP28 in 13 diseases based on the OPEN TARGET platform, such as cancer or begin tumor, nutritional or metabolic disease, and gastrointestinal disease." (PMID 37450415, 2023).
cancer (continued). "After a series of analyses, we observed a statistically negative correlation between T cell NK and USP28 expression in most cancers based on the XCELL algorithm." (PMID 37450415, 2023). "Moreover, USP28 also stabilizes other oncoproteins, such as STAT3 or LIN28, promoting cancer cell viability and growth." (PMID 34685632, 2021). "Similar to USP28, the role of PIRH2 has been a subject of controversy in cancer treatment." (PMID 34685632, 2021). "USP28 can counteract the activity of FBW7 and promote c-MYC stability in cancer cells." (PMID 29415985, 2018). "After a thorough literature search, we could not locate any publications that performed a pan-cancer analysis of USP28 across different tumor types." (PMID 37450415, 2023). "As recent reports described USP25 as an oncoprotein in diverse tumor entities, the co-inhibition of USP25 by the current available USP25/USP28 dual specific inhibitors for cancer therapy might, therefore, not be an issue." (PMID 34685632, 2021). "Ubiquitin-specific peptidase 28 (USP28) is a deubiquitinase (DUB) enzyme belonging to the USP family, which was discovered to be closely related to cell-cycle progression, DNA repair, apoptosis, proliferation, and tumorigenesis, which suggested USP28 might be a promising target for cancer therapy." (PMID 37450415, 2023). "Thus while USP28 is elevated in BRCA1 mutant cancers, we could not detect its regulation directly downstream of BRCA1." (PMID 34465787, 2021). "Thus, factors such as USP28 and PRKD1 may provide attractive anti-cancer targets." (PMID 24623306, 2014).
tumor (54 papers, 2014 to 2026). "Loss of USP28 reduces PD-L1 expression, increases effector cytokine production, and suppresses tumor growth in mice." (PMID 42189121, 2026). "To elucidate the possible involvement of USP28 in tumor progression, we investigated the correlation between USP28 expression and mutations in mismatch DNA repair (MMR) genes." (PMID 37450415, 2023). "Previously, we reported that loss of Usp28 affected the induction of lung squamous cancer, and its genetic loss affected overall tumour burden." (PMID 35364627, 2022). "We previously observed that genetic loss of USP28 affected tumour burden in a murine in vivo NSCLC model." (PMID 35364627, 2022). "Next, we analysed the expression of Usp28 and its substrates c‐Myc, c‐Jun and Notch1 at various grades in murine primary tumours, generated by intratracheal infection with a KP encoding AAV." (PMID 35364627, 2022). "Similar observations were made in other tumor entities, where loss of USP28 induced treatment resistance." (PMID 34611298, 2022). "While KPL mice developed both NSCLC entities, ADC and SCC, loss of USP28 strongly affected overall tumour induction and blocked SCC formation." (PMID 32128997, 2020). "As NOTCH signalling plays an important role in KRas‐induced tumour formation in the lung, loss of USP28 reduced overall tumour burden and, while blocking SCC formation, also reduced ADC tumour burden in the lung." (PMID 32128997, 2020). "Thus, USP28 missense mutations enable continued proliferation under stress conditions, potentially promoting genomic instability and driving tumor progression." (PMID 41365927, 2025). "Additionally, USP28 expression is strongly associated with the infiltration levels of neutrophils and NK cells in most tumor types." (PMID 37450415, 2023). "In line with this hypothesis, we indeed did observe that loss of USP28 reduced oncogenic cell proliferation and its genetic loss impaired tumour onset in vivo." (PMID 35364627, 2022). "Additionally, loss of USP28 attenuated tumor growth in a mouse xenograft model." (PMID 38498222, 2024). "Preclinical studies have demonstrated that several selective USP28 inhibitors exhibit potent anti‐tumor effects." (PMID 40855785, 2026). "In NSCLC, USP28 has been identified as a potential driver of oncogenesis, contributing to tumor growth and progression through the stabilization of specific substrates involved in cell proliferation and survival pathways." (PMID 40855785, 2026). "The USP28 inhibitor AZ1 exerts anti‐tumor effects in NSCLC, and it synergizes with cisplatin to enhance therapeutic efficacy." (PMID 40855785, 2026). "In contrast, there are reports about USP28 acting as a tumor suppressor, and USP28 affecting FBXW7-autoubiquitination causing FBXW7 stabilization which results in degradation of target proteins." (PMID 40456839, 2025). "Novel targets such as nuclear receptor-binding SET domain protein 3 (NSD3), lysine methyltransferase 2 D (KMT2D), and ubiquitin-specific peptidase 28 (USP28), are related to tumor microenvironment (TME) and immune cells." (PMID 39544292, 2024). "Together, these results indicate that loss of USP28 decreased MAST1 protein level and suppressed tumor growth upon cisplatin treatment." (PMID 38498222, 2024).